ERBB4 (erb-b2 receptor tyrosine kinase 4)
Diseases named in the same sentence as ERBB4 in open-access papers (continued):
Sharing a sentence is not in itself a finding about the gene and the disease.
brain cancer (5 papers, 2016 to 2025). A primary or metastatic malignant neoplasm affecting the brain. "Mutations targeting the ErbB4 gene have been functionally characterized in some non-brain cancers, like non-small cell lung cancer." (PMID 36119496, 2022). "As previously discussed, mutations of ErbB4 have been described in a range of brain cancers and the presence of such activating mutations could identify patients who may benefit from ErbB4 therapeutics." (PMID 36119496, 2022). "ErbB2 Receptor Tyrosine Kinase 4 (ERBB4) is expressed throughout normal brain and is an oncogene in several pediatric brain cancers; therefore, we investigated ERBB4 as a prognostic marker and therapeutic target in GBM." (PMID 30044378, 2018). "It is likely that ErbB4 can also be activated by other receptors expressed in brain cancers." (PMID 36119496, 2022). "The effective use of agents that inhibit ErB4 in brain cancer will require research that identifies pro-tumorigenic forms of ErbB4; targeting tumor suppressor forms of ErbB4 with drugs could obviously be detrimental to patients." (PMID 36119496, 2022). "Therefore, when determining the role of ErbB4 in brain cancers, other mechanisms of activation apart from ligand engagement must be considered." (PMID 36119496, 2022). "Despite high expression in the brain and a critical role in brain development, remarkably little is known about the potential signalling activity of ErbB4 in brain cancer.This review focuses on the unique biology of ErbB4 in the brain, and in particular, highlights brain cancer research findings." (PMID 36119496, 2022). "It is also involved in the activation of CRC PTEN was identified as a tumor suppressor and therapeutic target for cancer WIPF1 is a candidate prognostic marker for BC, brain cancer, and CRC ErbB4 gene plays a significant role in BC prognostics and therapy." (PMID 34575665, 2021).
cardiac hypertrophy (5 papers, 2020 to 2025). "For example, cardiac endothelial-specific ErbB4 deficiency has been shown to attenuate myocardial hypertrophy and fibrosis under stress, while ErbB4 activation can promote cardiomyocyte hypertrophy." (PMID 40746531, 2025). "We found that this NRG1/ErbB4 signaling axis contributes to the development of myocardial hypertrophy during prediabetic cardiac injury." (PMID 40746531, 2025). "In cardiomyocytes, miR-146a dampens metabolic activity through inhibition of receptor tyrosine-protein kinase erbB-4 (ERBB4), an important modulator of physiological pregnancy-induced cardiac hypertrophy." (PMID 32252821, 2020). "However, miR-146 was also found in endothelial cell-derived exosomes and was shown to be transferred to cardiomyocytes where it negatively regulates Erb-B2 Receptor Tyrosine Kinase 4 (Erbb4), known to be involved in cardiac hypertrophy and metabolism." (PMID 33013428, 2020). "Furthermore, both drugs, through the inhibition of TEC and ERBB4, might reduce nitric oxide production, promoting atrial endothelial dysfunction, enhanced cardiac hypertrophy and fibrosis, and reduced capillary formation." (PMID 40744952, 2025). "However, TBX5, TBX20, ERBB4, and GRK5, which have been linked to the proliferation of fetal and neonatal cardiomyocytes [TBX5, TBX20, ERBB4] and cardiac hypertrophy [GRK5], were upregulated in the CM1 cluster, as well as in Fetal cardiomyocytes." (PMID 35860330, 2022).
Cerebral ischemia (5 papers, 2017 to 2024). Restriction of arterial blood supply to the brain associated with insufficient oxygenation to support the metabolic requirements of the tissue. "Similar results were shown with erbB4 knockout mice following stroke where neuroprotection by NRG-1 against cerebral ischemia was prevented in the mice with erbB4 deleted in parvalbumin (PV)-positive interneurons." (PMID 38638304, 2024). "The precise role of ErbB4 in brain ischemia remains largely unknown." (PMID 28724924, 2017).
esophageal cancer (5 papers, 2014 to 2021). A primary or metastatic malignant neoplasm involving the esophagus. "The observed p.S239P mutation resides in ERBB4 extracellular dimerizing domain, has formerly been reported in esophageal cancer as ERBB4-activating mutation and might represent a bypass-mechanism for erlotinib-resistance, but the role of ERBB4-mutants in TKI-resistance needs further clarification." (PMID 29899852, 2018). "Overall, our results suggest the potential application of miRNA-140-5p as a potential therapeutic moiety in the treatment of ErbB4 mediated/overexpressed esophageal cancers." (PMID 25538945, 2014). "ErbB4 is an important member of ErbB subfamily of tyrosine kinases receptor with overexpression in several tumors; however its biological role in esophageal cancer is poorly understood till date." (PMID 25538945, 2014). "Furthermore, we have carried out experiments to prove ErbB4 as a potential molecular/pharmacological target in the treatment of esophageal cancers." (PMID 25538945, 2014). "Taken together, miRNA-140-5p could act as a potential molecular target in ErbB4 overexpressing ESCC cell lines paving the way for effective esophageal cancer treatment." (PMID 25538945, 2014). "miR-302b suppresses tumor growth and transcription factors protein expression through targeting erb-b2 receptor tyrosine kinase 4 (ERBB4), interferon regulatory factor 2 (IRF2), and Cxc chemokin receptor 4 (CXCR4) in esophageal cancer." (PMID 33729388, 2021). "We first determined the expression levels of ErbB4 protein and miR-302b in three different esophageal cancer cell lines (Eca109, Ec9706, and TE-1) and one esaphagel normal cell line (Het-1A)." (PMID 24438167, 2014). "Summing up, we have successfully showed that miRNA-140-5p could directly target ErbB4 protein in EC9706 and TE-1A esophageal cancer cell lines to control the cell proliferation and repress the cell invasion and migration." (PMID 25538945, 2014).
metastatic tumors (5 papers, 2011 to 2023). "Our findings point to potential predictive value of ERBB4 overexpression as a biomarker for metastatic disease in ES." (PMID 23681745, 2013). "Given that ERBB4 suppresses anoikis and increases migration and invasion of ES cells in vitro, and enhances their metastatic capacity in vivo, we wondered whether ERBB4 expression correlates with metastatic disease in ES patients." (PMID 23681745, 2013). "For metastatic tumors from GENIE, a total of sixteen candidate genes had significantly higher SNV frequencies in MMR-d tumors, of which six genes (KMT2D (33.3%), JAK1 (28.3%), FAT1 (21.7%), ERBB4 (20.0%), KMT2A (20.0%), and MGA (20.0%)) had a SNV frequency ≥ 20% in MMR-d tumors." (PMID 36675550, 2023).
atherosclerosis (4 papers, 2008 to 2025). A disease characterized by the build-up of fatty material and calcium deposition in the arterial wall resulting in partial or complete occlusion of the arterial lumen. "CSF1 can contribute to atherosclerosis development via fatty streak formation and progression to complex fibrous lesions, and CD44 may enhance atherosclerosis pathogenesis via reactive oxygen species, whereas neuregulin and ERBB4 are necessary for vascular growth and development." (PMID 18987747, 2008).
autism spectrum disorder (4 papers, 2017 to 2025). A spectrum of developmental disorders that includes autism, and Asperger syndrome. "Enhanced ERBB4 signaling has been implicated in Angelman syndrome, an autism spectrum disorder marked by behavioral traits such as increased desire for social interaction, developmental delay, severe speech impairment, and a happy demeanour, although aggressive behavior has sometimes been reported." (PMID 29045412, 2017). "Because in addition to ErbB4 the alternative splice variants of many at-risk genes are frequently aberrant in Scz and affective, addictive and autism spectrum disorders, single-pair probe ISH at a cellular level could generally advance our understanding of isoform changes in psychiatric disorders." (PMID 29264769, 2018).
bladder tumors (4 papers, 2006 to 2022). "Related studies have found that low ErbB4 levels were associated with high-grade, muscle-invasive, and poor survival for bladder tumors." (PMID 36118856, 2022). "It has been show that there were significant different levels of ErbB4 protein expressions between a sample of bladder tumors and normal margins." (PMID 32795296, 2020).
COVID-19 (4 papers, 2021 to 2024). A disease caused by infection with severe acute respiratory syndrome coronavirus 2. "In addition, some mito-DEGs were reversely altered in the AT2 and AT1 subsets (e.g., LRRK2, PID1, SOD2, CLIC4, and ERBB4) or showed altered expression in the AT2 or AT1 subset in patients with COVID-19 (–D)." (PMID 35844544, 2022). "Notably, in the proteins related to COVID-19, we also found several proteins involved in apoptosis, such as FGFR2 and ERBB4." (PMID 38575325, 2024).
diabetic nephropathy (4 papers, 2018 to 2024). "A variant in ERBB4 has been previously associated with diabetic nephropathy, and ERBB4/Erbb4 has been shown to be differently expressed in human in vitro and in murine models of renal disease." (PMID 35227251, 2022). "Thus, inhibition of Erbb4-IR can protect against diabetic nephropathy by upregulating renal miR-29b." (PMID 37449045, 2023). "Moreover, there is evidence that ERBB4-IR plays a role in CKD and diabetic nephropathy." (PMID 38768139, 2024).
ependymoma (4 papers, 2015 to 2025). A WHO grade II, slow growing tumor of children and young adults, usually located intraventricularly. "A study of a large cohort of pediatric ependymoma patients found that co-expression of ErbB4 with ErbB2 occurred in over 70% of cases and was associated with higher proliferative index and poorer patient survival." (PMID 36119496, 2022). "We observed somatic mutations or fusions in NF2 in 41% (7/17) of meningiomas, 5% (3/60) of ependymomas, and 25% (3/12) of schwannomas, as well as rare fusions in ERBB4, YAP1, and/or QKI in 10% (6/60) of ependymomas." (PMID 37492101, 2023).
metabolic syndrome (4 papers, 2021 to 2023). A cluster of metabolic risk factors for CARDIOVASCULAR DISEASES and TYPE 2 DIABETES MELLITUS. "ErbB4 has been linked to the risks of type II diabetes and metabolic syndrome." (PMID 35705996, 2022). "Taken together, these results indicated that ErbB4 may mediate the function of PVN on metabolic syndrome." (PMID 37060105, 2023).
metastatic melanoma (4 papers, 2014 to 2021). A melanoma that has spread from its primary site to another anatomic site. "Moreover, recent findings about somatic mutations that activate ErbB4 in metastatic melanoma have started to support a casual role of ErbB4 in carcinogenesis and to support the development of tools, such as ErbB4 antibodies, to target ErbB4 in cancer." (PMID 24438167, 2014).
ovarian tumor (4 papers, 2011 to 2025). "However, several groups have studied the expression and clinical importance of ERBB4 in ovarian tumors." (PMID 27129169, 2016).
psychosis (4 papers, 2011 to 2023). "In this study, we used conditional Erbb4 mutants to examine the effects of inhibitory interneuron dysfunction on key neuroimaging markers associated with psychosis in humans." (PMID 36573631, 2023). "In summary, our study provides direct evidence linking inhibitory interneuron dysfunction in the Erbb4 mutant mice to analogues of in vivo neuroimaging alterations previously identified in psychosis and individuals at clinical high-risk for psychosis." (PMID 36573631, 2023). "To determine the neuronal populations implicated in “late” NMDAR-driven psychosis, we analyzed the effect of the inducible ablation of NMDARs in ErbB4-expressing cells in mice during late adolescence using a pharmacogenetic approach." (PMID 34899420, 2021). "Here, we sought to determine how inhibitory interneuron dysfunction in Erbb4 mutants affects in vivo neuroimaging readouts commonly used in psychosis research: arterial spin labeling (ASL) to measure CBF, and 1H-MRS to measure glutamate, glutamine, and GABA levels in the hippocampus." (PMID 36573631, 2023). "We hypothesized that if NMDAR deletion in PV-positive is insufficient to trigger psychosis-like changes during adulthood, extension to the larger population of ErbB4-positive cells may lead to such phenotype." (PMID 34899420, 2021). "We performed Sanger sequencing of all 28exons in ERBB4, as well as part of the promoter and part of the3′UTR sequence, hypothesizing that rare deleterious variants would befound in 188 cases with mood-incongruent psychosis from the GAIN BP study." (PMID 21637803, 2011).
Sepsis (4 papers, 2018 to 2025). Sepsis is defined as life-threatening organ dysfunction caused by a dysregulated host response to infection. "Overexpression of miR-146a mitigates myocardial injury by negatively regulating NF-κB activation and inflammatory cytokine production via targeting ErbB4 in LPS-induced sepsis." (PMID 40041174, 2025). "For example, over-expression of miR-146a mitigates myocardial injury by negatively regulating NF-κB activation and inflammatory cytokine production via targeting Erb-B2 receptor tyrosine kinase 4 (ErbB4) in LPS-induced sepsis." (PMID 34757596, 2022). "Next, miR‐146a inhibits sepsis‐induced myocardial dysfunction by targeting ErbB4 (An, Feng, Xi, Xu, & Sun, 2018), and miR‐21‐3p modulates sepsis‐induced cardiac dysfunction by targeting SORBS2." (PMID 32369227, 2020). "We aimed to identify the role and potential regulatory mechanism of miR-146a in sepsis-induced cardiac dysfunction with the induction of ErbB4 signaling." (PMID 30224945, 2018). "In conclusion, our results demonstrated that the overexpression of miR-146a mitigates myocardial injury by negatively regulating NF-κB activation and inflammatory cytokine production via targeting ErbB4 in LPS-induced sepsis." (PMID 30224945, 2018).
skin cancer (4 papers, 2019 to 2021). "Another ERBB family member variant, ERBB4 E452K, appeared mainly in skin cancers and has been confirmed to increase activity." (PMID 30709382, 2019). "In summary, these data indicate that during tumorigenesis LRIG2 increases skin tumor progression, associated with activation of EGFR/ERBB4‐MAPK signaling." (PMID 31580518, 2019). "ERBB4 is a well-known oncogene in skin cancer and found to be mutually exclusive with ERBB2." (PMID 34899838, 2021).
type 2 diabetes (4 papers, 2012 to 2023). "Some of these hub proteins are the components of our identified enriched pathways, including calcium signaling, g-secretase mediated ErbB4 signaling, adipocytokine signaling, insulin signaling, AKT signaling and type II diabetes mellitus pathways." (PMID 23369358, 2013).
brain tumors (3 papers, 2021 to 2024). "We observed lower incidences of KDD in ERBB2, ERBB3 and ERBB4 than EGFR, with distributions mirroring those of other observed oncogenic mutations in brain tumors and NSCLC13–17." (PMID 33654076, 2021). "In summary, research is limited regarding individual ErbB4 isoform expression in brain tumors." (PMID 36119496, 2022).
colon adenoma (3 papers, 2017 to 2021). An adenoma that arises from the colon. "The increased co-expression of KITENIN and ErbB4-CYT-2 promotes the transition from colonic adenoma to adenocarcinoma in the tumor microenvironment associated with APC loss." (PMID 34935584, 2021). "The increased co-expression of ErbB4-CYT-2 with KITENIN promoted the transition of colon adenoma to adenocarcinoma in tumor microenvironment of APC loss." (PMID 32117908, 2020).
colorectal adenocarcinoma (3 papers, 2006 to 2021). The most common type of colorectal carcinoma. "However, another study demonstrated that ERBB4 could promote the progression of colorectal adenocarcinoma through epithelial-mesenchymal transition." (PMID 33446784, 2021).
cutaneous melanoma (3 papers, 2020 to 2021). A primary melanoma arising from atypical melanocytes in the skin. "The four ERBB tyrosine kinase family members [ERBB1 (epidermal growth factor receptor, EGFR), ERBB2 (HER2), ERBB3 (HER3), and ERBB4 (HER4)] (ERBB receptor family) have been shown, according to previous studies, to be related to the cutaneous melanoma." (PMID 33732282, 2021). "ERBB4 expression may not affect the prognosis of patients with cutaneous melanoma." (PMID 33732282, 2021). "Also, we found that ERBB1/2/3 and immune infiltration cells (B cells, CD4+ T cells of CD8+ T cells, macrophages, neutrophils, and dendritic cells) influenced the 5 years survival of patients with cutaneous melanoma, while ERBB4 may not affect the 5-year survival of cutaneous melanoma patients." (PMID 33732282, 2021).
dilated cardiomyopathy (3 papers, 2012 to 2021). Cardiomyopathy which is characterized by dilation and contractile dysfunction of the left and right ventricles. "Despite the normal heart morphology evident at birth, conditional ErbB4 KO mice developed severe dilated cardiomyopathy and conduction abnormalities that lead to premature death." (PMID 34408653, 2021). "Ventricular muscle with the inactivation of ErbB4 may lead to severe dilated cardiomyopathy, and knockout of NRG-1 worsen the ventricular function post-Dox-induced cardiac injury." (PMID 30224945, 2018). "The search for differentially deregulated set of genes in dilated cardiomyopathy was performed by comparing the transcript levels from adult erbB4-KO, WTD and KOD relative to WT mouse hearts in hybridization experiments in microarrays containing over 8,500 mouse cDNA clones." (PMID 22970387, 2012).
head and neck squamous cell carcinoma (3 papers, 2014 to 2023). A squamous cell carcinoma that arises from any of the following anatomic sites: lip and oral cavity, nasal cavity, paranasal sinuses, pharynx, larynx, and salivary glands. "A significant tumor specific overexpression of all four ErbB receptors including EGFR, ErbB2, ErbB3, and ErbB4 has been reported in head and neck squamous cell carcinomas (HNSCC)." (PMID 24886178, 2014).
infarction (3 papers, 2015 to 2022). A localised pathological necrosis of tissue resulting from obstruction of the blood supply usually by a thrombus, an embolus, or vascular torsion. "In addition, another study revealed that in a model of ischemia–reperfusion (I/R) cardiac injury, miR-539-3p enhanced infarction area and stimulated oxidative stress, myocardial cell apoptosis, and reduced cardiac function recovery via targeting ErbB4." (PMID 35303885, 2022).
ischemic stroke (3 papers, 2017 to 2024). A stroke disorder caused by obstruction of blood flow to the brain, due to thrombotic (local blood clot formation) or embolic (due to a blood clot or other material traveling from another site) event. "A future direction is therefore examining the effects of manipulating ErbB4 expression on the pathophysiology of the ischemic stroke." (PMID 28724924, 2017). "In support of this hypothesis, ischemic stroke can induce ErbB4 expression in neurons and NRG1 ligand, possibly secreted from neuronal presynaptic terminals can positively regulate ErbB4 signaling." (PMID 31560696, 2019). "Collectively, our findings suggest that NRG1-AdMSCs transplantation after ischemic stroke can activate MAPK and Akt pathways, possibly through the upregulation of the NRG1 receptor, ErbB4." (PMID 31560696, 2019). "For example, in both in vitro OGD/R and in vivo ischemic stroke model (MCAO/R) models, integrin-alpha-5 (Itga5) and receptor tyrosine kinase (ErbB4) were up-regulated or down-regulated after reperfusion, respectively." (PMID 28724924, 2017).